CCL21 (C-C motif chemokine ligand 21)
Diseases named in the same sentence as CCL21 in open-access papers (continued):
Sharing a sentence is not in itself a finding about the gene and the disease.
AIDS (3 papers, 2010 to 2022). A syndrome resulting from the acquired deficiency of cellular immunity caused by the human immunodeficiency virus (HIV). "The International Cancer Institute now recognizes CCL21 as an effective drug in the treatment of AIDS and cancer." (PMID 36037155, 2022). "In addition to its anti-tumor activity, CCL21 is also effective in treating AIDS." (PMID 36037155, 2022). "We found that CCL19 but not CCL21 mRNA was increased 8-fold in lymph nodes at 12 weeks post infection, but only in animals that progressed to AIDS." (PMID 21203477, 2010).
aortic stenosis (3 papers, 2014 to 2022). Aortic valve stenosis is a aortic valve disease caused by the incomplete opening of the aortic valve. "Another study suggested that CCL21/CCR7 interactions was involved in left ventricular remodeling during pressure overload in patients with aortic stenosis." (PMID 36159993, 2022). "It has been shown that patients with symptomatic aortic stenosis have higher serum CCL21 level compared to healthy controls." (PMID 36684607, 2022). "Our main findings were: (i) Serum levels of CCL21 were markedly raised in patients with symptomatic aortic stenosis (AS, n = 136) as compared with healthy controls (n = 20)." (PMID 25398010, 2014).
atopic dermatitis (3 papers, 2009 to 2022). "Because DC migration to the lymph nodes is crucial for allergic dermatitis, we investigated the migratory activity of both DC subsets in response to CCL21, a “homing” chemokine expressed in the lymph nodes." (PMID 33037399, 2021). "In healthy skin immunostaining for CCL21 is negative, however it is expressed on dermal endothelial cells in atopic dermatitis." (PMID 19639049, 2009).
chondrosarcoma (3 papers, 2021 to 2023). A malignant cartilaginous matrix-producing mesenchymal neoplasm arising from the bone and soft tissue. "In vitro experiments using SW1353 chondrosarcoma cells showed that CCL21-activated CCR7 induced an EMT phenotype with expression of phospho-ERK, phospho-AKT, Slug and N-cadherin." (PMID 35203305, 2022). "In addition, CCL21 and CXC chemokine receptor 7 have been illustrated as important regulators in the EMT process in human chondrosarcoma." (PMID 34001131, 2021).
coronary artery disease (3 papers, 2012 to 2022). "A few studies have noticed elevated plasma levels of CCL19 and CCL21 in ApoE-/- mice with AS lesions, human CAP, and patients with coronary artery disease." (PMID 36187128, 2022).
diabetes (3 papers, 2011 to 2023). "In addition, higher levels of the cytokine receptors, sIL-6R and sTNFR1, and the chemokines, CCL19, CCL20, CCL21, and CXCL11, were also associated with a history of self-reported diabetes at the <10% level." (PMID 28753646, 2017). "We observed associations between self-reported diabetes and the chemokines previously reported in the literature, including CXCL10 and interleukin-8 (IL-8), as well as identified a number of novel associations such as: CCL19, CCL20, CCL21, CXCL6, and CXCL11." (PMID 28753646, 2017). "WP supplementation in the diabetes model was found to significantly increase CXCL12- and CCL21-mediated actin polymerization and chemotaxis in both B and T cells." (PMID 22070978, 2011). "Moreover, CCL21/CCR7 can recruit T cells to pancreatic islets and play an important role in inflammatory response in type 1 diabetes mellitus." (PMID 37845726, 2023).
diabetic nephropathy (3 papers, 2016 to 2021). "As for chronic inflammation, the elevated CCL21-mRNA in uEV might be a candidate biomarker for early recurrent diabetic nephropathy based on a recent study." (PMID 34638835, 2021).
fibrosarcoma (3 papers, 2015 to 2025). A malignant mesenchymal fibroblastic neoplasm affecting the soft tissue and bone. "In a subcutaneously injected fibrosarcoma tumor model,47Ch25h was present in tumor-associated endothelium while Ccl21 was absent." (PMID 39708807, 2025). "Expression of LIGHT in a fibrosarcoma cell line resulted in upregulation of CCL21 and MAdCAM-1 on tumor vasculature, facilitating recruitment of vast numbers of naive CD8+ T lymphocytes, which appeared to then be sufficiently activated in situ to facilitate rejection of established tumors." (PMID 29312327, 2017). "Similarly, the expression of LIGHT in a fibrosarcoma cell line resulted in upregulation of CCL21 and MAdCAM-1, facilitating the recruitment of vast numbers of naive CD8+ T lymphocytes, which were then sufficiently activated in situ to facilitate rejection of established tumors." (PMID 29312327, 2017).
glioblastoma (3 papers, 2023 to 2025). The most malignant astrocytic tumor (WHO grade IV). "Our result also provides a rationale to therapeutically target CCL21 as a potential novel treatment for glioblastoma." (PMID 39456552, 2024). "We provide important details to indicate that glioblastoma cell-secreted CCL21 plays a dual role both in recruiting plasmacytoid dendritic cells via binding to CCR7 and activating plasmacytoid dendritic cells through the CCR7/ACKR4—β-arrestin/CIITA pathway." (PMID 39456552, 2024). "Moreover, lymphatic endothelial-like cells are present in glioblastomas and promote the growth of CCR7-positive glioblastoma stem cells through CCL21-driven cholesterol metabolism." (PMID 40722703, 2025). "A recent study showed that lymphatic endothelial-like cells present in GBM could promote growth of CCR7-positive glioblastoma stem cells through CCL21 secretion." (PMID 39456552, 2024).
Granuloma (3 papers, 2010 to 2016). A compact, organized collection of mature mononuclear phagocytes, which may be but is not necessarily accompanied by accessory features such as necrosis. "Using granuloma suspensions in-vitro, we showed that the migration of DCs can be driven by CCL21 and that migration is somewhat less efficient when DCs are infected." (PMID 26515292, 2015). "Expression of the chemokines CCL21, CXCL1, CCL7 and CCL12 showed a significant correlation with the expression of procollagen genes and resembled the recruitment of HSCs into granulomas." (PMID 20161726, 2010). "The addition of BCG did not affect the migration index of granuloma cells in the absence of CCL21." (PMID 26515292, 2015).
leukemia (3 papers, 2007 to 2018). A malignant (clonal) hematologic disorder, involving hematopoietic stem cells and characterized by the presence of primitive or atypical myeloid or lymphoid cells in the bone marrow and the blood. "Accordingly, both CXCL12 and CCL21 induced transmigration of Eμ-Tcl1 Tg leukemias in transwell assays." (PMID 27843137, 2017). "CCL21 has also been implicated in the abnormal adhesion and migration of CD34+ cells in leukemia." (PMID 17506907, 2007). "Strikingly, only mice vaccinated with DC/CCL21 loaded with bacterial, viral or tumor antigens and not recipients of DC/control adenovirus loaded cells or no DCs had a marked increase in the systemic clearance of pathogens (bacteria; virus) and leukemia cells." (PMID 29617362, 2018).
metastatic melanoma (3 papers, 2011 to 2021). A melanoma that has spread from its primary site to another anatomic site. "A recent study demonstrated that VEGF-C gene expression strongly correlated with CCL21 expression and T cell inflammation in human metastatic melanoma, and serum VEGF-C concentrations were associated with both T cell activation and expansion." (PMID 29963266, 2018). "Suppression of CCL21 production was also reported in TDLN of patients with metastatic melanoma." (PMID 21811640, 2011).
multiple sclerosis (3 papers, 2015 to 2023). A progressive autoimmune disorder affecting the central nervous system resulting in demyelination. "Evidence for CCL21 synthesis in epithelial cells of human choroid plexuses from both control individuals without CNS inflammation and multiple sclerosis patients, could therefore be of relevance to the migration of T cells across the blood-CSF barrier in neuroimmune surveillance." (PMID 26942913, 2016).
osteoarthritis (3 papers, 2014 to 2020). A noninflammatory degenerative joint disease occurring chiefly in older persons, characterized by degeneration of the articular cartilage, hypertrophy of bone at the margins and changes in the synovial membrane. "Conditioned media from osteoarthritis tissues like cartilage, IFP, meniscus, and synovium induced and enhanced production of CXCL8 and CCL21 in the synoviocyte cell line." (PMID 32189997, 2020). "CCL21 and CCR7 are expressed in chronic articular inflammatory diseases such as osteoarthritis and rheumatoid arthritis." (PMID 30914733, 2019). "The expression levels of CCL19, CCL21 and their receptor CCR7 in AS (n = 31) and osteoarthritis (OA, n = 21) LT were analyzed via real-time polymerase chain reaction (RT-PCR) and immunohistochemistry (IHC)." (PMID 25260647, 2014).
systemic sclerosis (3 papers, 2022 to 2023). A chronic disorder, possibly autoimmune, marked by excessive production of collagen which results in hardening and thickening of body tissues. "Dysregulated CCL21 and CCL19, ligands of ACKR4, were also revealed in human PAH and CCL21 appears to be a potential biomarker for predicting the risk of PAH in systemic sclerosis." (PMID 37449198, 2023). "Ccl21, found by us to be upregulated by 3.26x in HO, 79.95x in CM, and 247.09 in HM, has a disputed value as a potential PAH biomarker in systemic sclerosis." (PMID 37367058, 2023).
thyroid cancer (3 papers, 2021). "Several researchers have additionally demonstrated that four chemokines, CXCL1, CCL5, CCL20 and CCL21, biologically affect thyroid cancer cells by modulating inflammation and the immune microenvironment." (PMID 33345267, 2021). "Most chemokines were downregulated in thyroid cancer, including CCL3, CCL4, CCL15, CCL21, and CXCL13." (PMID 33414407, 2021). "CCL21 is a ligand of the chemokine receptor CCR7, activation of which promotes thyroid carcinoma growth." (PMID 34522174, 2021).
ulcerative colitis (3 papers, 2021 to 2024). An inflammatory bowel disease involving the mucosal surface of the large intestine and rectum. "Studies have shown that inhibiting CCL21 expression can help alleviate clinical symptoms and intestinal tissue damage in mice with ulcerative colitis (UC)." (PMID 39881721, 2024).
acute myocardial infarction (2 papers, 2012 to 2025). Necrosis of the myocardium, as a result of interruption of the blood supply to the area. "(ii) In patients with HF following acute myocardial infarction (MI; n = 232), high versus low CCL21 levels 1 month post-MI were associated with cardiovascular mortality, even after adjustment for established risk factors." (PMID 22427939, 2012). "Additionally, sequence variations in the promoter regions of CCL19 and CCL21 have been associated with an increased susceptibility to myocardial infarction, while genetic predisposition to elevated circulating levels of CCL2 correlates with a heightened risk of stroke." (PMID 40236901, 2025).
adenomyosis (2 papers, 2022 to 2024). The growth of endometrial tissue inside the muscular wall of the uterine corpus. "Chemokine (C-C motif) ligand 21 (CCL21), related to immune system-associated signal transduction, was highly expressed after the GnRHa treatment, indicating that a molecular regulation may be involved in the improvement of endometrial receptivity in adenomyosis." (PMID 39201621, 2024). "The expression level of the endometrial receptivity marker HOXA10 was significantly increased after combined administration of GnRHa and CCL21 in the uterus of mice with adenomyosis." (PMID 35022045, 2022). "CCL21 can regulate the recruitment of Treg cells, which affect the receptivity of the endometrium in adenomyosis." (PMID 35022045, 2022). "After combined administration of GnRHa and CCL21 in the uterus of mice with adenomyosis, expression of the endometrial receptivity marker HOXA10 was significantly increased." (PMID 35022045, 2022). "Immunoreactive CCL21 is thought to regulate inflammatory events and participate in endometrial receptivity in adenomyosis." (PMID 35022045, 2022). "The immunoreactive chemokine CCL21 was found to be highly expressed after GnRHa treatment, and CCL21 combined with GnRHa is suggested to promote endometrial receptivity in adenomyosis." (PMID 35022045, 2022). "Our results indicate that when CCL21 and GnRHa were combined to treat mice with adenomyosis, they enhanced the expression of HOXA10 to promote endometrial receptivity." (PMID 35022045, 2022). "To further study the role of CCL21 in adenomyosis, we generated model mice with adenomyosis and treated them with GnRHa." (PMID 35022045, 2022). "KEGG pathway analysis illustrated the involvement of CCL21 in signaling molecules and interactions, signal transduction and the immune system, which suggests the potential influence of CCL21 dysregulation in adenomyosis." (PMID 35022045, 2022). "At the same time, our study has revealed that CCL21 is downregulated in the endometrium of adenomyosis patients." (PMID 35022045, 2022). "The expression of CCL21 was observed in the endometrium at the mid-secretory phase, especially in glandular epithelial cells, while it was significantly decreased in the endometrium of patients with adenomyosis." (PMID 35022045, 2022). "One focus of our next research will be determining whether CCL21 can regulate the endometrial immune environment by recruiting Tregs in adenomyosis and further improve the receptivity of the endometrium." (PMID 35022045, 2022). "CCL21 was noted among signaling molecules and interactions, signal transduction and the immune system, suggesting its potential role in the mechanism of GnRHa in the treatment of adenomyosis." (PMID 35022045, 2022). "Furthermore, the adenomyosis mice model were employed to explore the function of GnRHa and identified gene CCL21 on the endometrial receptivity." (PMID 35022045, 2022). "Therefore, the expression of CCL21 was decreased in patients with adenomyosis, and GnRHa treatment upregulated the expression of CCL21 in patients with adenomyosis." (PMID 35022045, 2022). "CCL21 was also reported to take part in the inflammatory reaction in adenomyosis." (PMID 35022045, 2022). "CCL21 levels were found to increase in the endometrium of patients with adenomyosis after GnRHa treatment, which may affect the outcome of pregnancy by regulating the recruitment of Tregs." (PMID 35022045, 2022). "The addition of CCL21 may further promote the therapeutic effect of GnRHa on adenomyosis, thereby improving endometrial receptivity." (PMID 35022045, 2022). "Chemokine (C-C motif) ligand 21 (CCL21) was found to be highly expressed in the eutopic endometrium after GnRHa treatment, which may be involved in the improvement of endometrial receptivity in adenomyosis." (PMID 35022045, 2022).
adenomyosis (continued). "The expression level of CCL21 was confirmed through RNA-Seq analysis and further validation, and its potential function was predicted through KEGG analysis and assessment of common chemokine function in adenomyosis." (PMID 35022045, 2022). "After 3–6 months of GnRHa treatment, the expression of CCL21 in the endometrium of adenomyosis patients increased to normal levels, consistent with our RNA-Seq and qPCR results." (PMID 35022045, 2022).
Alzheimer disease (2 papers, 2013 to 2025). A progressive, neurodegenerative disease characterized by loss of function and death of nerve cells in several areas of the brain leading to loss of cognitive function such as memory and language. "This network contains the proinflammatory cytokine Il1a, previously associated with Alzheimer’s disease, development and plasticity, immune associated genes (Cd80, Cr2, Cd27, Dapp1) and chemokines (Ccl3, Ccl4, Ccl21)." (PMID 23742273, 2013).
aneurysm (2 papers, 2009 to 2025). Bulging or ballooning in an area of an artery secondary to arterial wall weakening. "In addition, inflammatory factors such as C‐C motif chemokine ligand 21 (CCL21) may also promote angiogenesis and the migration of inflammatory cells in the formation of aneurysms." (PMID 40384564, 2025).
Arthritis (2 papers, 2021 to 2023). Inflammation of a joint. "Consistent with the in vitro findings, an in vivo study showed that CCL21-mediated arthritis favors the exacerbation of joint inflammation into bone erosion, and that this process was associated with M1-macrophages dependent Th17 polarization." (PMID 34220809, 2021). "Therefore, CCL21 is an potential target for RA therapy, as the suppression of CCL21-mediated inflammation may relieve erosive arthritis modulated by the interaction of M1 macrophages and Th17 cells." (PMID 34220809, 2021).
autoimmune thyroid disease (2 papers, 2025). Inflammatory disease of the thyroid gland due to autoimmune responses leading to lymphocytic infiltration of the gland. "In other words, CCL21 levels may be correlated with these core indicators of thyroid autoimmunity and dysfunction." (PMID 41234223, 2025). "LTβR‐mediated pathways further contribute to inflammation, and transgenic mice expressing CCL21 under the thyroglobulin promoter develop extensive lymphocytic infiltrates and HEVs within the thyroid, underscoring the key role of CCL21 in autoimmune thyroid disease." (PMID 40996881, 2025).
gastric adenoma (2 papers, 2018 to 2023). A neoplastic polyp that arises from the stomach. "In gastric adenomas, homeostatic chemokines (including CXCL13, CCLL9 and CCL21) were associated with the formation of TLS." (PMID 38110876, 2023).
gastric tumours (2 papers, 2018 to 2021). "Homeostatic chemokines play a central role in the development of secondary lymphoid organs and TLSs,4, 12 and our earlier data revealed transcripts for Cxcl13, Ccl19, Ccl21 and Cxcl12 in laser microdissected TLSs from 6‐month‐old gp130F/F mice with well‐established gastric tumours." (PMID 29417587, 2018).
head and neck squamous cell carcinoma (2 papers, 2014 to 2021). A squamous cell carcinoma that arises from any of the following anatomic sites: lip and oral cavity, nasal cavity, paranasal sinuses, pharynx, larynx, and salivary glands. "For example, increased expression of CCL19 and CCL21 by lymphatic endothelium in squamous cell carcinoma of the head and neck (SCCHN) promoted dissemination of CCR7+ tumor cells to secondary lymphoid tissues." (PMID 34503058, 2021).
infarction (2 papers, 2022 to 2023). A localised pathological necrosis of tissue resulting from obstruction of the blood supply usually by a thrombus, an embolus, or vascular torsion. "In a mouse model studying MI, the inhibition of CCL21 via intravenous injection of anti-CCL21 monoclonal antibodies led to the reduction of the infarction size after acute MI." (PMID 35600479, 2022).
influenza (2 papers, 2010 to 2021). An acute viral infection of the respiratory tract, occurring in isolated cases, in epidemics, or in pandemics; it is caused by serologically different strains of viruses (influenzaviruses) designated A, B, and C, has a 3-day incubation period, and usually lasts for 3 to 10 days. "Our data illustrated the significant enhancement of influenza-specific total IgG titer in mice immunized with either γ-Flu alone or with any of the three adjuvant combinations compared to mice treated with CCL21, Poly (I:C), and PBS (p < 0.001)." (PMID 34627297, 2021). "Thus, any adjuvant alone could be equally effective in modulating inflammatory responses of γ-inactivated influenza vaccine, but only the co-administration of CCL21 and Poly (I:C) significantly reduced the numbers of IL-10-producing cells in the lung after lethal viral challenge." (PMID 34627297, 2021).
Insulin resistance (2 papers, 2019). Increased resistance towards insulin, that is, diminished effectiveness of insulin in reducing blood glucose levels. "Chemokine (C-C motif) ligand 21 (CCL21), CYP27A1, RPRM, and CPB1 are novel biomarkers for the development of insulin resistance." (PMID 30678306, 2019).